CGN (cingulin)
Diseases named in the same sentence as CGN in open-access papers (continued):
Sharing a sentence is not in itself a finding about the gene and the disease.
cancer (10 papers, 2015 to 2024). A tumor composed of atypical neoplastic, often pleomorphic cells that invade other tissues. "This study pinpoints the c.3560C > T genetic variant within the tight junction protein CGN as a cancer susceptibility gene." (PMID 38424547, 2024). "Notably, this study addressed a potential targeted therapeutic strategy for cancers associated with CGN c.3560C > T by using the specific inhibitor NSC23766 to inactivate Rac1." (PMID 38424547, 2024). "Thus, this work strongly suggests that loss of ZO-1 in cancer is likely to affect cingulin/paracingulin localization." (PMID 25757376, 2015). "On the 28th day post-injection of cancer cells, the tumor growth, monitored by bioluminescence, was significantly promoted in CGN-mutant tumors compared to WT, and it cannot be suppressed by oxaliplatin treatment." (PMID 38424547, 2024). "In papillary and invasive adenocarcinomas, CGN was highly expressed at the membranes and it was detected in the cytoplasm of some cancer cells." (PMID 38338691, 2024). "We used the GENT2 database to compare the levels of CGN and PTPRR between normal and cancer tissues and found that CGN is downregulated in 19/35 cancers including CRC (red brackets) while PTPRR is downregulated in 16/35 including CRC." (PMID 39697634, 2024). "After variants calling from family-based germline genome sequence data, validation in a cancer patient cohort, and mechanistic studies for tumorigenesis evaluation, the germline variant CGN c.3560C > T of tight junction protein, cingulin (CGN), was identified as germline cancer risk variant." (PMID 38424547, 2024). "Interestingly, in some invasive adenocarcinomas, CGN expression was faint at the membranes of certain cancer cells." (PMID 38338691, 2024). "In some invasive adenocarcinomas, CGN was faintly expressed at the membranes of some cancer cells." (PMID 38338691, 2024). "CGN expression was highest in cell lines showing characteristics of well-polarized epithelial cells with TJ, such as Eph4, Caco2 and mCCD, and showed low or undetectable expression in several cancer lines, such as MDA-MB-231, Hela, and U-2OS." (PMID 35203278, 2022). "CGN pretreatment might increase the cellular ROS level in A549 cells, which thereby promotes the killing ability to cancer cells." (PMID 28415625, 2017). "Such an example may be illustrated by the recent discovery of LKB1, inactivated in a variety of cancers, as an activator of p114RhoGEF-driven junction assembly, which occurs via recruitment by cingulin and PATJ junctional adaptors." (PMID 25757376, 2015). "Tight junction (TJ) protein cingulin (CGN) and transcription factor forkhead box protein O1 (FOXO1) contribute to the development of various cancers." (PMID 38338691, 2024). "Collectively, the rearrangement of F-actin network into contractile stress fibers can be only observed in the cancer cells harboring CGN c.3560C > T, but not CGN WT or KO." (PMID 38424547, 2024). "There are likely additional mechanisms that can lead to decreased levels of CGN and PTPRR because not all cancers show increased expression of miR-100 or miR-125b, but the data are in agreement that decreased levels of CGN and PTPRR correlate with cancer." (PMID 39697634, 2024). "We thus sought to test if decreased expression of CGN and PTPRR due to increased expression of miR-100 and miR-125b might be observed in CRC and other cancers." (PMID 39697634, 2024).
tumor (9 papers, 2020 to 2024). "In addition, CGN expression was negatively associated with the tumor-promoting factors BIRC5 and CXCR4." (PMID 35223987, 2022). "To study the in vivo tumor growth inhibition produced by NSC23766 against CGN c.3560C > T-mutant tumors, we injected the mice’s cecal wall with Luc-expressing CGN c.3560C > C or c.3560C > T HT-29 cells and treated them with saline or NSC23766." (PMID 38424547, 2024). "WB results also showed that protein level of CGN in the tumor tissues was significantly lower than that in the normal tissues (p < 0.001)." (PMID 35223987, 2022). "Based on these previous findings and our research, it is presumed that the upregulation of CGN can inhibit tumor development." (PMID 35223987, 2022). "When compared with the normal tissues, the expression levels of CGN in the tumor tissues were significantly reduced (p < 0.001)." (PMID 35223987, 2022). "We analyzed the relationship between CGN expression and age, gender, tumor grade, tumor stage, T stage, N stage, and M stage." (PMID 35223987, 2022). "According to the HPA database, the CGN protein level in the tumor tissues was significantly lower than that in the normal tissues." (PMID 35223987, 2022). "The results showed that CGN expression decreased significantly with age, advanced tumor stage, high grade, and advanced T, N, and M stages." (PMID 35223987, 2022). "CFTR serves as a pivotal tumor suppressor through complex mechanisms; CGN, another downregulated gene, is located in the cytoplasmic face of tight junctions and plays an indispensable role in tumor cell polarization, proliferation and migration." (PMID 34830864, 2021). "Importantly, blocking Rac1 activity by a specific inhibitor NSC23766 reverses the EMT program and attenuates CGN-mutant tumor growth." (PMID 38424547, 2024). "This study found that CGN expression is negatively correlated with ccRCC clinical staging and M0 macrophage content, which explains that the latter changes with the progression of tumor staging in patients." (PMID 35223987, 2022). "In addition, a high level miR-125b was associated with lymph node metastasis and poor tumor differentiation, and the inverse relationship between miR-125b and CFTR/CGN was observed in both primary CRC and distant metastasis tissues." (PMID 34830864, 2021). "To examine whether miR-125b targets CFTR and CGN in human CRC, we analyzed the expression patterns of CFTR and CGN in the tissue microarray containing tumor-adjacent normal tissues, primary CRC tissues and distant metastatic tissues." (PMID 34830864, 2021). "The ligand-receptor pairs that commonly showed such differences across the ten tumor and matched tissue types included PLAU-ITGA5, LIPH-LPAR2, SEM14G-PLXNB2, SEMABD-TYROBP, CCL2-CCR5, CCL3-CCR5, and CGN-TYROBP." (PMID 34512714, 2021). "Some genes in this module were connected by processes proposed to be involved in tumor progression, such as DOC2A, CGN (Cingulin), PARD6B, NEDD4L, and SYT9 which belonged to the KEGG pathway, tight junction (TJ) (hsa04530), and GEO term, cell junctions (GO:0030054)." (PMID 32605588, 2020). "Consistently, xenograft tumors with WT CGN showed no sensitivity to NSC23766 treatment, but NSC23766 demonstrated the capacity to attenuate tumor growth harboring c.3560C > T." (PMID 38424547, 2024).
adenocarcinoma (3 papers, 2014 to 2024). A common cancer characterized by the presence of malignant glandular cells. "On the other hand, we have showed that adenocarcinoma phenotype is associated with a higher expression of CLD3 and CGN, whereas SCC often loses the expression of these genes." (PMID 24625834, 2014).
infection (2 papers, 2013 to 2022). The state of being infected such as from the introduction of a foreign agent such as serum, vaccine, antigenic substance or organism. "Then, we found that CGN, MAP3K5, GATA4 and RUNX1 related to tight junction were upregulated during DTMUV infection, indicating that these genes may play an important role in DTMUV entry." (PMID 35585616, 2022).
kidney diseases (2 papers, 2022 to 2025). "To elucidate the role of ISG-T cells in immune-mediated kidney diseases, we used a well-established murine cGN model." (PMID 40393992, 2025).
CGN also shares sentences with these, for which no sentence is quoted: asthma (2 papers); brain cancer (1); colon adenocarcinoma (1); ductal carcinomas (1); eczema (1); epithelioid mesotheliomas (1); hay fever (1); intestinal diseases (1); lobular carcinomas (1); squamous cell carcinoma (1).